FOXM1 (forkhead box M1)
Diseases named in the same sentence as FOXM1 in open-access papers (continued):
Sharing a sentence is not in itself a finding about the gene and the disease.
glioma (continued). "Because of the diverse function of FoxM1 in glioma tumorigenesis and progression, a better understanding of FoxM1 signaling and function will help identify effective targets for gliomas therapy." (PMID 23991102, 2013). "We observed a significant correlation between FoxM1 and Anxa1 expression in glioma cells and provide evidence that FoxM1 promote glioma proliferation, migration, and angiogenesis by up-regulating Anxa1 expression." (PMID 23991102, 2013). "Overexpression of FoxM1 up-regulated Anxa1 expression, whereas suppression of FoxM1 expression down-regulated Anxa1 expression in glioma cells." (PMID 23991102, 2013). "To provide direct evidence that FoxM1 affect the angiogenic phenotype by regulating Anxa1 of glioma cells, we determined the angiogenic ability of the U-87MG-RNAi-Anxa1 and SW1088-FoxM1-RNAi cells using an endothelial cell tube formation assay." (PMID 23991102, 2013). "In gliomas, FOXM1 was recently shown to interact with β-catenin to promote the nuclear translocation of β-catenin to activate the expression of WNT target genes in glioma stem cells, leading to their self-renewal and tumorigenesis." (PMID 23386997, 2013). "Several studies have demonstrated the importance of FoxM1 in oncogenesis in a variety of malignancies, including gliomas." (PMID 23991102, 2013). "Our current study enriched the understanding of the mechanism of the FoxM1 on glioma carcinogenesis." (PMID 23991102, 2013). "Depletion of FOXM1 in glioma cells resulted in a reduction in cell proliferation and anchorage-independent colony formation on soft agar." (PMID 23229761, 2013). "Consistent with previous studies, we found that mRNA and protein levels of FoxM1 and Anxa1 were up-regulated in human glioma specimens and related to the poor outcome." (PMID 23991102, 2013). "In the present study, we show that Anxa1 expression related to FoxM1 expression in human glioma tissues and predict poor outcome." (PMID 23991102, 2013). "In the present study, we identified both FoxM1 and Anxa1 are overexpression in the primary glioma specimens, and predicts poor survival." (PMID 23991102, 2013). "Together, our results indicate that FoxM1 enhances the angiogenic ability of glioma cells by up-regulating the Anxa1 expression." (PMID 23991102, 2013). "PHGDH interacted with and stabilized FOXM1 at the protein level, promoting the proliferation, invasion and tumorigenicity of glioma cells." (PMID 23229761, 2013). "Next, we tested the function of FoxM1/Anxa1 interaction by assessing their roles in glioma cells biological behaviors." (PMID 23991102, 2013). "Additionally, FOXM1 expression in human glioma tissue correlates directly with glioma grade, and its level in human GBM tissue inversely correlates with patient survival." (PMID 41141395, 2026). "A previous study identified FoxM1 as a downstream target of the canonical Wnt/β-catenin signaling pathway, wherein its nuclear accumulation, in conjunction with β-catenin, enhances the expression of c-Myc and Cyclin D1 in glioma cells." (PMID 41323781, 2025). "Cumulatively, these data suggest that the R15 residue within the FoxM1 N-terminal domain may play a key role in the migration and invasion of glioma cells." (PMID 41323781, 2025). "The R15A mutation impaired FoxM1 transcriptional activity, hindered FoxM1 nuclear translocation and failed to promote the migratory and invasive behavior of glioma cells than other single arginine mutations." (PMID 41323781, 2025). "Study has also shown that HMGCL enhances H3K27ac modification by promoting acetyl-CoA production, and upregulates FOXM1 expression, which in turn promotes the nuclear translocation of β-catenin, ultimately contributing to glioma stem cell maintenance and glioblastoma multiforme progression." (PMID 41365992, 2025). "In addition to this, it has been shown that MYBL2 is a downstream effector of Akt/FOXM1 signaling in glioma." (PMID 40115748, 2025).
glioma (continued). "The FOXM1/β-catenin axis mediates stemness properties and tumorigenesis of glioma stem cells." (PMID 39594778, 2024). "Regarding glioma, FOXM1 is one of the most frequent molecular alterations in the malignancy." (PMID 38398118, 2024). "Additionally, FOXM1 plays a pivotal role in glioma development by facilitating the nuclear translocation of β‐catenin and augmenting its transcriptional activity in cells." (PMID 38063438, 2024). "Similarly, the expression of both STAT3 and FOXM1 was shown to be concurrent following radiation treatment in high-grade gliomas." (PMID 37821870, 2023). "circCCDC66 facilitated glioma cell migration and invasion through miR-320a/FOXM1 axis." (PMID 37588107, 2023). "Moreover, not only STAT3 but also STAT1 can control FOXM1 expression in different glioma cell lines (U87, A172, U251, and T98), influencing other signaling pathways implicated in inflammation, such as NF-κB." (PMID 37821870, 2023). "FOXM1 (forkhead box protein M1, also known as HNF-3, HFH-11, or Trident) is a transcription factor whose overexpression was implicated in the carcinogenesis of diverse tumors, especially glioma." (PMID 37821870, 2023). "In addition, we found that FOXM1 overexpression blocked the effects of Chalcone 9X on cell proliferation, apoptosis, and migration in glioma cells." (PMID 35978634, 2022). "Furthermore, overexpression and knockdown experiments in glioma cells revealed that FoxM1 is a key target of Bortezomib, since its downregulation appeared to underlie the cytotoxic effects of the inhibitor." (PMID 35409080, 2022). "Co-transfection of miR-320a or forkhead box M1 (FOXM1) plasmids into glioma cells could rescue the consequences of si-circCCDC66-induced cell growth inhibition to some extent." (PMID 36698408, 2022). "The present study hypothesized that DFS would exert a proliferation-inhibiting effect in GBM because of the fact that stemness and tumorigenicity are regulated by FOXM1/β-catenin interactions in glioma stem cells." (PMID 35978012, 2022). "We searched for transcription factors that are positively co-expressed with EIF4EBP1 in gliomas and found EIF4EBP1 mRNA expression to be significantly and positively associated with the mRNA expression levels of MYBL2, FOXM1, ETS1, HIF-1A, JUN, E2F1, and E2F6 in the REMBRANDT dataset." (PMID 35228525, 2022). "Recently, studies show that NOX4 stimulates FOXM1 expression and further LDHA expression by increasing mitochondrial ROS in glioma, and FABP4-associated ROS production could induce FOXM1 expression." (PMID 36407005, 2022). "Moreover, the upregulation of RFC5 transcriptionally activated by Forkhead box M1 (FOXM1) leads to temozolomide resistance in glioma cells." (PMID 35210438, 2022). "In addition, FOXM1 overexpression dismissed the Chalcone 9X effects on cell proliferation, apoptosis, and migration in human glioma cell lines." (PMID 35978634, 2022). "Furthermore, it has been demonstrated in TCGA glioma patient cohorts that FOXM1 and MYBL2 expression are linked in gliomas." (PMID 35409080, 2022). "Then Chalcone 9X with 100 μmol/L was added into the glioma cells with p-FOXM1 or p-NC for 48 h." (PMID 35978634, 2022). "Results showed that the protein expressions of FOXM1 were upregulated after p-FOXM1 transfection into U87 and T98G cells, which suggested FOXM1 was successfully transfected into glioma cells, while FOXM1 protein levels were reduced after treating with Chalcone 9X (p < 0.001)." (PMID 35978634, 2022). "So we concluded that MYBL2 is of importance downstream factor of Akt/FoxM1 signaling to stimulate advancement of glioma, and could be considered as a promising gene for molecular targeting therapy and biomarker for radiotherapy of glioma." (PMID 35935338, 2022). "Interestingly, FOXM1 can bind directly to β-catenin to promote its nuclear localization and transcriptional activity in glioma; this provides an addition link between FOXM1 and β-catenin." (PMID 34205406, 2021).
glioma (continued). "FOXM1 expression levels were also related to the prognosis of glioma patients in the TCGA database." (PMID 34740322, 2021). "Besides, our data also have shown that FOXM1 expression was positively correlated with the expression of circCCDC66 in glioma tissues." (PMID 34252882, 2021). "Additionally, FOXM1 functions to promote glioma proliferation, stimulate epithelial-mesenchymal transition (EMT), strengthen the resistance of GBM cells to radiotherapy, and facilitate self-renewal and of glioma stem cells (GSCs)." (PMID 35004326, 2021). "FOXM1 activates MMP2 to enhance the invasiveness of gliomas." (PMID 33423377, 2021). "In addition to ovarian cancer, FOXM1 is linked to CSC phenotypes in other cancers, including lung, liver, glioma, breast, colon, prostate, endometrial, and embryonal carcinoma." (PMID 34205406, 2021). "Given that higher expression of NOX4 and FOXM1 predicted a worse prognosis in glioma, and based on reports that NOX4 promotes cell glycolysis in a variety of human malignancies, including glioblastoma, we explored the impact of NOX4 and FOXM1 on aerobic glycolysis in glioblastoma cells." (PMID 34740322, 2021). "Additionally, miR-320 was decreased while forkhead box protein M1 (FoxM1) was increased in radioresistant glioma tissues obtained from GBM patients." (PMID 35047931, 2021). "Dai and colleagues showed that FOXM1 enhances MMP-2 transcription to promote glioma progression." (PMID 32035486, 2020). "In this study, we aimed to identify genes related to the pathogenesis and progression and prognosis of gliomas based on GEO data sets and investigate the effects of ASPM on the biological functions of glioma cells, as well as the role of FoxM1 in the up‐regulation of ASPM expression in gliomas." (PMID 32667745, 2020). "In addition, the analysis of the CGGA data set, TCGA data set and clinical samples consistently suggested that the expression of FoxM1 was higher in gliomas and predicted a poor prognosis of glioma patients." (PMID 32667745, 2020). "Interestingly, via analyzing clinical samples from our department and public datasets from TCGA, we found that FOXM1 and Survivin were widely overexpressed in glioma patients." (PMID 31796105, 2019). "To confirm whether Survivin was an important downstream effector of FOXM1, we firstly measured the mRNA levels of FOXM1 and Survivin in six glioma cell lines: U251, U87, LN229, A172, SF295, and SF268." (PMID 31796105, 2019). "In addition, we also measured the expression level of the FOXM1–Survivin axis in clinical glioma samples and analyzed its relation with patient prognosis." (PMID 31796105, 2019). "The present study demonstrated that down-regulating the FOXM1–Survivin axis could be an important molecular mechanism for using bortezomib in treating gliomas." (PMID 31796105, 2019). "In addition to glioma, several other tumors have shown the upregulation of both FoxM1 and WNT/β-catenin including medulloblastoma, colon cancer and hepatocellular carcinoma." (PMID 29423068, 2018). "Mechanistically, FoxM1/ADAM17 axis activated the EGFR/AKT/GSK3β signaling pathway and ADAM17/EGFR/GSK3β axis could maintain FoxM1 stability in glioma cells." (PMID 29700308, 2018). "Overexpressing FoxM1 or ADAM17 increased the mesenchymal phenotype of glioma cells, which could be reversed by silencing FoxM1 or ADAM17." (PMID 29700308, 2018). "Accordingly, it confirmed that FoxM1 was a critical regulator for MES transition in glioma cells." (PMID 29700308, 2018). "Furthermore, FoxM1/ADAM17 axis promoted the tumorigenicity of glioma cells and the progression of GBM." (PMID 29700308, 2018). "Furthermore, ADAM17 knockdown downregulated mesenchymal markers expression and elicited E-cadherin expression, which is consistent with the results of FoxM1 knockdown in glioma cells." (PMID 29700308, 2018). "Herein, we demonstrated that if Akt can regulate MYBL2 and FoxM1 expression in glioma cells." (PMID 28784180, 2017).
glioma (continued). "However, further investigation is necessary to elucidate the mechanism of TAGLN2 regulation of FoxM1 axis in glioma." (PMID 29110682, 2017). "Moreover, high FoxM1 and UBE2C expression levels in gliomas were closely associated with a poor prognosis." (PMID 28767320, 2017). "Univariate Cox regression analysis indicated that the clinical stage (HR = 1.833, 95% CI: 1.395–2.409, p < 0.001) and high expression of MYBL2 (HR = 3.619, 95% CI: 2.075–6.313, p < 0.001) and FoxM1 (HR = 0.336, 95% CI: 0.187–0.602, p < 0.001) were unfavorable prognostic factor in glioma patients." (PMID 28784180, 2017). "They found that interacting β-catenin with FoxM1 could increase the expression of Wnt/β-catenin target genes, thus promoting the cell proliferation and growth of gliomas." (PMID 28837560, 2017). "In addition, we determined FoxM1 expression in the same series of glioma specimens; a pattern similar to that of UBE2C expression was observed." (PMID 28767320, 2017). "In addition, high FoxM1/UBE2C expression was significantly correlated with poor prognosis in glioma." (PMID 28767320, 2017). "We further revealed that high FoxM1 expression enhanced the tumorigenicity of glioma cells." (PMID 28767320, 2017). "Kindlin-2 was also shown to promote FoxM1 expression, which could also induce the nuclear localization of β-catenin in glioma cells." (PMID 27713156, 2016). "The potential for FOXM1 inhibition in glioma treatment has been suggested previously." (PMID 27764801, 2016). "FOXM1 transcriptional activities are required for its oncogenic functions; however, FOXM1 could also promote β-catenin nuclear translocation independently of its DNA-binding activity, which may play a role in glioma formation." (PMID 25609649, 2015). "Interestingly, we found that the oncogenic transcription factor FOXM1 was also downregulated in PHDGH-silenced glioma cells." (PMID 23229761, 2013). "Next, we examined FoxM1 mRNA expression in glioma specimens." (PMID 23991102, 2013). "Furthermore, the FoxM1 expression affected the tumorigenic ability of glioma cells in vitro and in vivo, including proliferation, migration and angiogenesis, which consistent with other studies." (PMID 23991102, 2013). "Furthermore, FoxM1 is substantially elevated in several aggressive human carcinomas and can contribute to oncogenesis in many tissue types, including gliomas, breast, hepatocellular, prostate, lung, and colorectal cancers." (PMID 23991102, 2013). "In addition, a strong correlation of the co-expression of FoxM1 and Anxa1 were observed in patients with gliomas." (PMID 23991102, 2013). "From these data, we concluded that PHGDH could stabilize FOXM1 protein from degradation in glioma cells." (PMID 23229761, 2013). "Therefore, our study provides both clinical and mechanistic evidences that FoxM1 directly regulates Anxa1 expression and showed a novel mechanism by which FoxM1 promotes glioma proliferation, migration and angiogenesis." (PMID 23991102, 2013). "Furthermore, we found that FoxM1 promote glioma cells proliferation, migration, and angiogenesis by directly regulating Anxa1 expression." (PMID 23991102, 2013). "Finally, we provided evidence that Anxa1 is required for FoxM1-induced gliomas progression in model mice." (PMID 23991102, 2013). "Moreover, overexpression of Anxa1 in depleted FoxM1 glioma cells recovered the ability of tumorigenicity." (PMID 23991102, 2013). "Therefore, FoxM1 overexpression contributes directly to Anxa1 overexpression in glioma cell proliferation, migration and angiogenesis." (PMID 23991102, 2013). "Moreover, we showed that FoxM1 promotes Anxa1 transcription in human glioma cells and Anxa1 is required for FoxM1-induced cell proliferation, migration and angiogenesis." (PMID 23991102, 2013).
glioma (continued). "In cancer development and progression, FOXM1 has been implicated in regulating the expression of the human endothelial cell caveolae-marker CAV-1 and Foxm1 expression has also been linked to growth of glioma cells in tumour angiogenesis." (PMID 24391823, 2013). "Furthermore, we performed transwell assays to assess the function role of FoxM1/Anxa1 in glioma cells migration." (PMID 23991102, 2013). "Moreover, FoxM1 overexpression counteracted the suppression of TFAM by siRNA in glioma cells." (PMID 41323781, 2025). "Based on the findings, one reasonable hypothesis is that FoxM1 activity is mitigated by N-terminal autorepression, which can be destabilized with R15, contributing to the transcriptional activation, nuclear translocation and malignant function of FoxM1 in glioma cells." (PMID 41323781, 2025). "In addition to its role in chemotherapy and radiotherapy resistance, FOXM1 is involved in reducing autophagic death in glioma cells by regulating the expression of Ubiquitin-conjugating enzyme E2C (UBE2C), which plays a critical role in the development of gliomas." (PMID 39594778, 2024). "Moreover, Chalcone 9X treatment could repress the mRNA and protein expressions of FOXM1 in human glioma cell lines, which was an oncogene that could promote the progression and malignancy of glioma." (PMID 35978634, 2022). "Therefore, we uncovered a novel way that Chalcone 9X could inhibit FOXM1 expression and repress the progression and biofunctions of glioma cells, which might be a potential therapeutic drug for treating human glioma." (PMID 35978634, 2022). "In this study, we found that Chalcone 9X treatment repressed mRNA and protein expressions of FOXM1 in glioma cells after treating for 48 h, which suggested that Chalcone 9X might regulate cell proliferation and migration by reducing the oncogenic factor FOXM1 in glioma." (PMID 35978634, 2022). "For example, FOXM1 could elevate the MYBL2 level to promote the progression of human glioma." (PMID 35978634, 2022). "Results indicated that Chalcone 9X repressed the protein levels of FOXM1 in a dose-dependent manner in U87 and T98G cells after 48 h (p < 0.05), which might suggest that Chalcone 9X might play some roles in glioma cell proliferation via the oncogenic factor FOXM1." (PMID 35978634, 2022). "FOXM1 was an oncogene that could promote the development and malignancy of glioma." (PMID 35978634, 2022). "In addition, miRNA-216b could suppress FoxM1 expression in human glioma, osteosarcoma, liver cancer, cervical cancer, melanoma, and NSCLC." (PMID 34470640, 2021). "Moreover, FoxM1 is involved in brain development as well as self-renewal of glioma stem cells." (PMID 33691791, 2021). "Thus, a highly activated FOXM1–Survivin axis could greatly promote glioma cell proliferation and malignant transformation, and enhance resistance and survival of glioma cells under stress." (PMID 31796105, 2019). "We next confirmed whether the FoxM1/ADAM17 axis regulated the tumorigenicity of glioma cells." (PMID 29700308, 2018). "In addition, FoxM1 activated EGFR/AKT/GSK3β signaling pathway in glioma cells." (PMID 29700308, 2018). "However, the role of FoxM1 in regulating the MES transition in glioma is still unclear." (PMID 29700308, 2018). "Forkhead box transcription factor M1 (FoxM1) is a typical proliferation-specific transcription factor, which is up-regulated in various types of human malignancies, including lung cancer, hepatoma, prostate cancer, breast cancer, sarcoma, pancreatic cancer and glioma." (PMID 28767320, 2017). "Moreover, to uncover the potential molecular mechanisms by which TAGLN2 promote glioma development, we detect the expression change of FoxM1, an oncogenic transcriptional factor that regulates some key mediators of cell cycle progression, including CDK2, cyclin B1, cyclin D1, p21 and p27." (PMID 29110682, 2017).